FOXF1 (forkhead box F1)
Diseases named in the same sentence as FOXF1 in open-access papers (continued):
Sharing a sentence is not in itself a finding about the gene and the disease.
breast invasive ductal carcinomas (2 papers, 2016 to 2025). "In invasive ductal carcinomas of the breast, FOXF1 is frequently hypermethylated and consequently silenced, suggesting a potential tumor suppressor function." (PMID 40869921, 2025).
cleft palate (2 papers, 2010 to 2019). Cleft palate is a fissure type embryopathy that affects the soft and hard palate to varying degrees. "We recently showed that neural crest-specific inactivation of either Foxf1 or Foxf2 caused cleft palate but did not significantly affect mandible and tongue development." (PMID 30638444, 2019). "Similarly, FOXF1 and Foxf1, but not FOXC2 or Foxc2, are clearly associated with abnormalities of intrinsic pulmonary vasculature and lung lobation while inactivation of FOXC2 and Foxc2, but not FOXF1 or Foxf1, is associated with cleft palate." (PMID 19822228, 2010).
Duodenal stenosis (2 papers, 2014 to 2024). The narrowing or partial blockage of a portion of the duodenum. "Given the findings in family 3 and the fact that FOXF1 alterations were associated with intestinal abnormalities, we propose that patients with gut malrotation, pyloric or duodenal stenosis, or gall bladder agenesis should be tested for FOXF1 mutations and CNVs." (PMID 25472632, 2014). "We propose that patients with gut malrotation, pyloric or duodenal stenosis, and gall bladder agenesis should be tested for FOXF1 alterations." (PMID 25472632, 2014).
Fanconi anemia (2 papers, 2022 to 2023). Fanconi anemia (FA) is a hereditary DNA repair disorder characterized by progressive pancytopenia with bone marrow failure, variable congenital malformations and predisposition to develop hematological or solid tumors. "FOXF1 is a part of the Fanconi anemia protein complexes to respond to damages in the DNA." (PMID 36101460, 2022).
Intestinal malrotation (2 papers, 2019 to 2024). An abnormality of the intestinal rotation and fixation that normally occurs during the development of the gut. "Finally, patient 5 had a large duplication on 16q24.1 that included the FOXF1 locus, previously implicated in syndromic forms of intestinal malrotation." (PMID 30632303, 2019).
liver cancer (2 papers, 2018 to 2020). An epithelial or non-epithelial malignant neoplasm that arises from the liver. "However, FOXF1 may be also considered a tumor suppressor since the loss of FOXF1 is associated with poor prognosis in liver cancer patients." (PMID 30360388, 2018).
ovarian carcinoma (2 papers, 2021 to 2024). A malignant neoplasm originating from the surface ovarian epithelium. "However, of the four TFs (PITX1, RARA, FOXF1/A1, and BHLHE41/40) that matched the binding motifs in DEG promoters, only one, FOXA1, has previously been implicated in ovarian cancer specifically." (PMID 34215221, 2021).
Patent ductus arteriosus (2 papers, 2019 to 2024). In utero, the ductus arteriosus (DA) serves to divert ventricular output away from the lungs and toward the placenta by connecting the main pulmonary artery to the descending aorta. "FOXF1 was implicated in the disorder through cardiac anomaly related gene ontologies while FOXF1 and MYH11 were implicated through patent ductus arteriosus." (PMID 39480826, 2024).
stenosis (2 papers, 2011 to 2021). "Haploinsufficiency of Foxf1 leads to a phenotype similar to Shh null mutant mice including hypoplastic lungs and lobulation defects, oesophageal and tracheal stenosis, or oesophageal atresia and tracheo-oesophageal fistula." (PMID 22132119, 2011).
acute lung injury (1 paper, 2023). A condition of lung damage that is characterized by bilateral pulmonary infiltrates (pulmonary edema) rich in neutrophils, and in the absence of clinical heart failure. "Additionally, using heterozygous Pdgfb-iCreER/Foxf1+/− mice, they demonstrate that deletion of one allele of Foxf1 was enough to increase the susceptibility of these mice to acute lung injury (ALI)." (PMID 38274049, 2023).
bipolar disorder (1 paper, 2014). A disorder of the brain that causes unusual shifts in mood, energy, activity levels and the ability to carry out day-to-day tasks. "The 16q23.3 duplication is also inherited from the father with bipolar disorder, suggesting that genes other than FOXF1 may be responsible for the patient’s autistic and emotional disorders." (PMID 25472632, 2014).
Borderline intellectual disability (1 paper, 2019). Borderline intellectual disability is defined as an intelligence quotient (IQ) in the range of 70-85. "One patient in the previously reported FOXF1 duplications paper harbored a duplication similar in size and location to our patient, and also presented with similar neurological features including borderline intellectual disability, but no intestinal malrotation or cardiac defects." (PMID 30632303, 2019).
bovine tuberculosis (1 paper, 2024). "Other genes found in the present study related to immunity and adaptation in literature were DNAJC17 (heat tolerance in Zebu cattle), GCHFR, MDGA2 (heat stress in cows), FOXF1, NKG7 (bovine tuberculosis response), and SIGLEC10." (PMID 39766784, 2024).
colon cancer (1 paper, 2013). "Our finding that FOXF1 was downregulated in the BRAF mutated cohort suggests that this gene might also play a role in oncogene-induced senescence in colon cancer." (PMID 23324568, 2013).
Congenital alveolar capillary dysplasia (1 paper, 2022). "Analyses of genes related to surfactant deficiency and congenital alveolar capillary dysplasia were normal: ATP-binding cassette sub-family A member 3 (ABCA3), surfactant pulmonary-associated protein C and B (SFTPC and SFTPB, respectively) and forkhead box protein F1 (FOXF1)." (PMID 35321730, 2022).
depressive disorder (1 paper, 2024). A melancholy feeling of sadness and despair. "We observed that genes connected with blood-brain barrier dysfunction, depressive disorders, and inflammation (CCR7, FOXF1) were enriched in SS relative to AA mice." (PMID 39629138, 2024).
Ehlers-Danlos syndrome (1 paper, 2024). The Ehlers–Danlos syndromes (EDS) are a clinically and genetically heterogeneous group of heritable connective tissue disorders (HCTDs) characterized by joint hypermobility, skin hyperextensibility, and tissue fragility. "The gene ontologies for list 8+ linked CDC42EP2, FOXF1, SGCA, and SORBS1 to Megacystis-Microcolon-Intestinal Hypoperistalsis Syndrome while CDC42EP2 and CNN1 linked to Classical-like Ehlers-Danlos Syndrome." (PMID 39480826, 2024).
gastroesophageal reflux disease (1 paper, 2024). A chronic disorder characterized by reflux of the gastric and/or duodenal contents into the distal esophagus. "For instance, gastroesophageal reflux disease (GERD) has a known heritability estimate of roughly 31% based upon twin and family studies, with known risk genes including FOXF1, MHC, and CCND1." (PMID 38527901, 2024).
glioma (1 paper, 2024). A benign or malignant brain and spinal cord tumor that arises from glial cells (astrocytes, oligodendrocytes, ependymal cells). "For instance, FOXQ1 and FOXF2 were highly expressed in glioma, FOXF1 in LUAD, and GATA4 in CHOL and LIHC, all consistent with previous studies." (PMID 39345334, 2024).
Granuloma (1 paper, 2025). A compact, organized collection of mature mononuclear phagocytes, which may be but is not necessarily accompanied by accessory features such as necrosis. "Among structural cells, the expression of key tissue development genes (MAPK14, GATA6, FOXF1, VEGFA) were markedly elevated in both endothelial and epithelial cell populations derived from MAH granulomas." (PMID 41586350, 2025).
holoprosencephaly (1 paper, 2016). Holoprosencephaly (HPE) is a complex brain malformation resulting from incomplete cleavage of the prosencephalon, occurring between the 18th and 28th day of gestation, and affecting both the forebrain and face, which results in neurological manifestations and facial anomalies of variable severity. "However, only mutations of HOXD13 and FOXF1 have been reported in humans with VACTERL association, while SHH and GLI2 mutations are associated with holoprosencephaly." (PMID 28003020, 2016).
Holt-Oram syndrome (1 paper, 2024). Holt-Oram syndrome (HOS) is the most common form of heart-hand syndrome and is characterized by skeletal abnormalities of the upper limbs and mild-to-severe congenital cardiac defects. "FOXF1 dysregulation or mutation may be present in patients with Holt-Oram Syndrome, particularly those with pulmonary anomalies." (PMID 39480826, 2024). "The gene ontologies for list 4+ linked FOXF1, MYH11, and TAGLN to Holt-Oram Syndrome." (PMID 39480826, 2024). "We propose that FOXF1, MYH11, and TAGLN are novel genes in Holt-Oram Syndrome." (PMID 39480826, 2024).
infantile hemangiomas (1 paper, 2022). "FOXF1 has also been linked to a number of immune cells, shedding light on the pathophysiology of infantile hemangiomas and the intricate interaction that occurs." (PMID 35992538, 2022). "In conclusion, our research looked at transcriptome changes in infantile hemangioma and found FOXF1 to be a novel biomarker of infantile hemangioma with a good diagnostic value using several analysis approaches." (PMID 35992538, 2022). "We found the gene set most associated to infantile hemangioma by intersecting the elevated genes with the genes acquired by WGCNA, with FOXF1 serving as the hub gene." (PMID 35992538, 2022). "FOXF1 was found to be a reliable biomarker of infantile hemangiomas in our research of transcriptome changes in infantile hemangiomas." (PMID 35992538, 2022). "Our study reveals the value of FOXF1 in infantile hemangiomas, where the role of FOXF1 was previously unknown." (PMID 35992538, 2022). "FOXF1 has a high AUC value in infantile hemangioma, and the AUC value in both ROC curve and PRC curve is greater than 0.9, indicating that FOXF1 is very robust in the diagnosis of infantile hemangioma." (PMID 35992538, 2022).
Infertility (1 paper, 2024). "Other etiological possibilities are a diabetic mother, a baby born out of infertility treatment, and exposure to lead, anticonvulsants, estrogen or progesterone-containing compounds, or alcohol during the period of embryogenesis causing mutations in the genes like HOXD13, FOXF1, and ZIC3." (PMID 39463584, 2024).
intestinal pseudo-obstruction (1 paper, 2024). A type of ILEUS, a functional not mechanical obstruction of the INTESTINES. "FOXF1 downregulation has been implicated in intestinal pseudo-obstruction though research is lacking." (PMID 39480826, 2024).
Lewis Lung Carcinoma (1 paper, 2024). "Expression of FOXF1 was examined in an orthotopic mouse model of NSCLC using Lewis Lung Carcinoma (LLC) cells." (PMID 38589650, 2024).
liver cirrhosis (1 paper, 2019). "Increased fibrosis in Foxf1-deficient mice was associated with the appearance of liver tumors, a finding consistent with increased tumor formation in patients with liver cirrhosis." (PMID 30670377, 2019).
lymph node metastasis (1 paper, 2020). "Even an immunohistochemical staining-based study demonstrated positively correlated FOXF1 expression in many NSCLCs with lymph node metastasis." (PMID 32370197, 2020).
lymphoma (1 paper, 2022). A malignant (clonal) proliferation of B- lymphocytes or T- lymphocytes which involves the lymph nodes, bone marrow and/or extranodal sites. "FOXF1, FOXK2, FOXO1, FOXO3, and FOXP1 were differentially expressed in at least five subtypes of lymphoma." (PMID 36292640, 2022).
Megacystis (1 paper, 2024). Dilatation of the bladder postnatally. "We propose that CDC42EP2, FOXF1, SGCA, and SORBS1 are novel genes in Megacystis-Microcolon-Intestinal Hypoperistalsis Syndrome." (PMID 39480826, 2024).
multisystemic smooth muscle dysfunction syndrome (1 paper, 2024). A spectrum of conditions caused by monoallelic pathogenic variants in ACTA2. "The gene ontologies for list 5+ linked FOXF1, KCNMB1, MYH11, and PLN to Multisystemic Smooth Muscle Dysfunction Syndrome." (PMID 39480826, 2024). "We propose that FOXF1, KCNMB1, and MYH11 are novel genes in Multisystemic Smooth Muscle Dysfunction Syndrome." (PMID 39480826, 2024).
oral diseases (1 paper, 2023). "In the context of oral diseases, ADSC-EVs have been shown to regulate multiple conditions, preventing the growth and fibrosis of fBMFs via the miR-375/FOXF1 axis." (PMID 38059910, 2023).
postmenopausal osteoporosis (1 paper, 2021). Metabolic disorder associated with fractures of the femoral neck, vertebrae, and distal forearm. "In ovariectomized (OVX) mice, knockdown of FoxF1 with siRNA significantly reduced OVX-induced bone loss by enhancing bone formation, suggesting that FoxF1 may be a marker factor for bone formation and a therapeutic target for postmenopausal osteoporosis." (PMID 35153742, 2021).
Pulmonary hemorrhage (1 paper, 2014). Pulmonary hemorrhage is a bleeding within the lungs. "The majority of mice with heterozygous loss-of-function of Foxf1 exhibit neonatal lethality with evidence of pulmonary hemorrhage in some of them." (PMID 24722050, 2014).
respiratory failure (1 paper, 2023). The significant impairment of gas exchange within the lungs resulting in hypoxia, hypercarbia, or both, to the extent that organ tissue perfusion is severely compromised. "Human FOXF1 mRNA was decreased in the lungs of patients diagnosed with hypoxemic respiratory failure." (PMID 38274049, 2023).
Sepsis (1 paper, 2020). Sepsis is defined as life-threatening organ dysfunction caused by a dysregulated host response to infection. "FENDRR, the FOXF1 adjacent non-coding developmental regulatory RNA, plays as a hub regulator mediating 14 sepsis modules in the lncRNA-module interaction network." (PMID 32471511, 2020).
Stroke (1 paper, 2019). Sudden impairment of blood flow to a part of the brain due to occlusion or rupture of an artery to the brain. "Positive expression of inflammation-associated stroke vasculomes (BRM, IκB, Foxf1, and ITIH-5), were quantified using immunofluorescent techniques and analyzed with Image J software." (PMID 30739275, 2019). "Further analysis revealed, a significant upregulation of the inflammation-associated stroke vasculome including BRM, IκB, Foxf1, and ITIH-5 up to 10 folds after OGD relative to ambient conditions (p’s < 0.05)." (PMID 30739275, 2019). "Expression analysis 7 days post EPC transplantation revealed a significant downregulation of Foxf1 protein expression of stroke-EPC animals compared to stroke-vehicle animals (Student t-test; p < 0.05) in the whole ipsilateral cortex lysates." (PMID 30739275, 2019). "Western blot analysis demonstrated the protein expression of inflammation-associated stroke vasculomes BRM, IkB, and Foxf1 in ipsilateral cortex lysates 7 days post EPC transplantation." (PMID 30739275, 2019). "In vitro detailed analyses of the human endothelial cells (HEN6) during OGD indicated a massive upregulation of inflammation-associated stroke vasculome (BRM, IkB, Foxf1, ITI-H5) relative to ambient conditions." (PMID 30739275, 2019). "Western blot analysis demonstrated the protein expression of inflammation-associated stroke vasculomes BRM, IkB, and Foxf1 in whole ipsilateral striatum lysates 7 days post EPC transplantation." (PMID 30739275, 2019). "Inflammation-associated stroke vasculome including Brahma (BRM), IκB (also called NFκB inhibitor), Foxf1, and ITIH-5 stainings were carried out in the peri-infarct area of the cortex and striatum." (PMID 30739275, 2019). "Similarly, positive expression of inflammation-associated stroke vasculomes (BRM, IκB, Foxf1, and ITIH-5), were quantified using immunofluorescent techniques and analyzed with Image J software." (PMID 30739275, 2019). "The inflammatory genes in the stroke vasculome include Brahma (BRM), IκB (also called NFκB inhibitor), Foxf1, and ITIH-5." (PMID 30739275, 2019). "The “sick” stroke genes associated with regulation and modulation of the inflammatory response after stroke include Brahma (BRM), NF-kb inhibitor kappa B alpha (IkB), Forkhead box F1 (Foxf1), and Inter-alpha-trypsin inhibitor (ITI-H5)." (PMID 30739275, 2019). "There were significant downregulations of BRM, IκB, Foxf1, and ITIH-5 expression in the peri-infarct area of the cortex of stroke-EPC animals compared to stroke-vehicle animals at 7 days post EPC transplantation (Student t-test; p’s < 0.05)." (PMID 30739275, 2019). "There were not significant differences of protein level of Foxf1 of stroke-EPC relative to stroke-vehicle animals (Student t-test; p > 0.05) in the whole ipsilateral striatum lysates 7 days post EPC transplantation." (PMID 30739275, 2019).
tendinopathy (1 paper, 2022). "Previously, there have been a few reports of differential promoter methylation of Mmp25, Foxf1, Leprel2, Igfbp6 and Peg12 in tendinopathy through genome-wide analysis." (PMID 35860629, 2022).
von Hippel-Lindau disease (1 paper, 2022). An autosomal dominant disorder caused by pathogenic variants in the VHL gene, leading to an increased risk of various benign and malignant tumors, including hemangioblastomas, retinal hemangiomas, endolymphatic sac tumors, renal cell carcinoma, and pheochromocytomas.